CBS (cystathionine beta-synthase)
Diseases named in the same sentence as CBS in open-access papers (continued):
Sharing a sentence is not in itself a finding about the gene and the disease.
neuroblastoma (8 papers, 2015 to 2024). Neuroblastoma (NB) is the most common solid, extracranial childhood tumor. "Along with the up-regulated AHCY, MYCN-amplified neuroblastoma cells have elevated levels of the CBS gene, encoding cystathionine beta synthase." (PMID 36361596, 2022). "GPX4 dependency in cancer cell lines was associated with enhanced expression of cystathionine beta-synthase (CBS), the rate-limiting enzyme for transsulfuration, with neuroblastoma being among the cancer entities with the highest CBS expression." (PMID 35484422, 2022). "In primary neuroblastomas, differences in CBS expression correlated with histone modifications and methylation of intragenic CpGs dependent on genomic MYCN status." (PMID 35484422, 2022). "In order to further establish if the overproduction of endogenous H2S leads to enhanced cell death under ischemic conditions, we overexpressed CBS in undifferentiated neuroblastoma SH-SY5Y cells." (PMID 25873304, 2015). "It was found that the endogenous level of H2S was markedly reduced upon hypoxic stress generated by Na2S2O4 in human neuroblastoma cells (SH-SY5Y), and CBS over-expression attenuated hypoxia-induced cell apoptosis." (PMID 37892173, 2023). "CBS, AHCY and PHGDH expression was also elevated in mass spectrometry-based global proteomes from MYCN-amplified neuroblastoma tumors." (PMID 35484422, 2022). "In the present study, the expression of CBS was confirmed in the RVLM and in SH-SY5Y cells, a neuroblastoma cell line." (PMID 36421438, 2022). "In a panel of 32 neuroblastoma cell lines, MYCN or MYC amplification or translocation in adrenergic subtypes was accompanied by upregulated CBS expression, while MYC translocation/activation in mesenchymal cell lines was not." (PMID 35484422, 2022). "Moreover, four genes from the methionine metabolism gene set, such, AHCY, CBS, DNMT3A, and MTAP, are markers of poor prognosis for neuroblastoma and breast, but not for colon and lung, cancer patients." (PMID 36361596, 2022).
Obesity (8 papers, 2014 to 2022). Accumulation of substantial excess body fat. "The specific downregulation of renal CBS may contribute to decreased H2S production, which could be a pathogenic mechanism of obesity." (PMID 29998554, 2018). "In the kidney, the suppressed CBS may contribute to reduced H2S production resulting in associated complications during obesity, which suggest a new potential therapeutic target of obesity." (PMID 29998554, 2018). "The hypothalamic CBS (cystathionin-β-synthase)/H2S pathway reduces obesity and improves insulin sensitivity through brain–adipose interactions." (PMID 35743160, 2022). "In the central nervous system, the CBS/H2S pathway in the paraventricular nucleus improved obesity and insulin sensitivity by regulating the neuroendocrine hormones via the brain–adipose interaction in the HFD rats." (PMID 35681432, 2022). "High-fat diet, obesity, and insulin resistance modify the CBS/CSE/H2S system in the liver and adipose tissue." (PMID 31531184, 2019). "In conclusion, our results revealed that CBS was selectively downregulated in both diet and gene‐induced obesity models." (PMID 29998554, 2018). "In addition to MAP2K3-B and PPARG2, autoantibodies to OSBPL11, CBS and TAL were also associated with cases and may be relevant to the pathophysiology of T2DM or obesity." (PMID 26606528, 2015).
Parkinson disease (8 papers, 2020 to 2025). A progressive degenerative disorder of the central nervous system characterized by loss of dopamine producing neurons in the substantia nigra and the presence of Lewy bodies in the substantia nigra and locus coeruleus. "Parkinson’s disease (PD) is manifested by motor system abnormalities, and decreased H2S production caused by down-regulation of CBS in the substantia nigra in PD animal models has been documented." (PMID 36039860, 2022). "In Parkinson's disease (PD), H2S mitigates mitochondrial dysfunction caused by CBS depletion." (PMID 41192145, 2025). "However, in other CNS diseases (e.g., Alzheimer’s disease and Parkinson’s disease), CBS expression and H2S levels in the CNS are significantly decreased." (PMID 32365821, 2020). "The fact that Parkinson’s patients treated with benserazide showed increased homocysteine plasma levels is also encouraging as this could be interpreted as a result of CBS inactivation." (PMID 32365821, 2020). "Differences are observed for Parkinson’s disease versus controls, Parkinson’s disease versus PSP and Parkinson’s disease versus CBS." (PMID 32671340, 2020). "There are no reports of altered CBS activity in Parkinson’s disease." (PMID 35276958, 2022).
colitis (7 papers, 2013 to 2024). Inflammation of the colon. "We further explored whether CBS is involved in CRC tumorigenesis in vivo using a colitis-associated CRC mouse model." (PMID 38490069, 2024). "We previously reported that CBS was the major enzymatic source of colonic H2S, but this was based largely on our observation that CHH, an inhibitor of CBS, caused a dramatic exacerbation of colitis in rats, that was more profound than was seen with inhibitors of CSE." (PMID 23940796, 2013). "This reduction of H2S synthesis well fits with the downregulation of CBS protein and mRNA expression in the colon of infected mice during colitis." (PMID 29636751, 2018). "Treatment with a nonspecific CTH inhibitor propargylglycine exacerbated DSS-induced colitis in mice, and mRNA expression of three H2S-producing enzymes (CTH, MPST, and cystathionine β-synthase [CBS]) and H2S production was upregulated in the colon mucosa in the experimental colitis of mice/rats." (PMID 36768979, 2023). "In a mouse model of dextran sodium sulfate (DSS)-induced colitis, CBS and CSE expression increased in the gut following DSS administration, and inhibition of the CSE with PAG worsened markers of inflammatory disease, suggesting that H2S has anti-inflammatory effects in colitis." (PMID 33330130, 2020). "Based on pharmacological studies (i.e., using inhibitors of CBS and CSE), CBS appeared to account for the majority of the observed increase in colonic H2S synthesis during colitis." (PMID 23940796, 2013).
glioblastoma (7 papers, 2018 to 2025). The most malignant astrocytic tumor (WHO grade IV). "An association with CBS expression and hypoxia has been established; when researchers subjected an in vitro model of U87-MG human glioblastoma cells and PC12 pheochromocytoma cells to hypoxic conditions, they reported increased transcription of CBS mRNA and protein synthesis." (PMID 33212887, 2020). "Apolipoprotein C1 promotes glioblastoma development by inhibiting ferroptosis through reduced CBS activity and increased GSH synthesis." (PMID 40165005, 2025). "In glioblastoma cells with high expression of apolipoprotein C1, the expression of CBS can be increased, which can stimulate the transsulfuration pathway, increase GSH synthesis, and induce ferroptosis resistance." (PMID 41154707, 2025). "It is therefore possible that high CBS expression as well as high levels of sulfane sulfur in T98G glioblastoma cells allow them to maintain a high antioxidant capacity." (PMID 41154707, 2025). "High CBS and CDO1 expression, as well as high levels of sulfane sulfur in T98G glioblastoma cells, suggests that sulfur metabolism is a critical determinant of tumor redox balance." (PMID 41154707, 2025). "In relation to glioblastoma formation, CBS overexpression seems to attenuate rather than supporting gliomagenesis." (PMID 37300955, 2023). "CBS may affect the increase in L-cysteine levels and thus GSH production in glioblastoma cells." (PMID 41154707, 2025). "Therefore, it is possible that modulation of the activity of both CBS and CDO1 may affect the antioxidant potential and survival of T98G glioblastoma cells, which we intend to verify in further studies." (PMID 41154707, 2025). "Therefore, it is rather the activation and not the inhibition of CBS that could potentially play an anti-tumoral effect in glioblastoma." (PMID 37300955, 2023).
Hepatic steatosis (7 papers, 2015 to 2025). Steatosis is a term used to denote lipid accumulation within hepatocytes. "CBS deficiency can lead to hepatic steatosis, inflammation and fibrosis in animal models; nevertheless, the correlation between CBS and NASH remains undetermined." (PMID 41567634, 2025). "Patients with CBS deficiency also have hepatic steatosis which is accompanied by perisinusoidal or central venous fibrosis and fibrosis of hepatic arterioles." (PMID 26192994, 2015). "It has been shown that CBS-deficient mice develop inflammation, fibrosis, and hepatic steatosis." (PMID 26192994, 2015). "Continued on the previous study, we identified that ATF6 ameliorates liver steatosis and inflammation by upregulating CBS expression and H2S synthesis via SIRT1 sulfhydration." (PMID 38007457, 2023). "The key enzymes of the TSP, cystathionine β-synthase (CBS) and cystathionine γ-lyase (CSE), are highly expressed in the liver and deficient CBS and CSE expression causes hepatic steatosis, inflammation, and fibrosis in animal models." (PMID 33807699, 2021). "The CBS-KO rabbit showed HHcy, dyslipidemia, a short life span, hepatic steatosis and other lesions." (PMID 33054837, 2020). "In addition, the mechanism by which ATF6 regulates H2S synthesis to ameliorate liver steatosis, and the role of CBS and inflammatory factors in liver metabolism remains uncertain." (PMID 38007457, 2023). "In alignment with our findings, a mouse model of fatty liver disease also presented with diminished CBS and transsulphuration metabolites, which negatively impacts glutathione metabolism, thus corroborating the critical participation of these selenium-related pathways in NAFLD pathogenesis." (PMID 34869521, 2021). "However, gastric infusion of vitamin B and betaine complex significantly decreased the plasma levels of TG, TC and LDL-C in the CBS-KO rabbits, and alleviated hepatic steatosis compared to the untreated animals." (PMID 33054837, 2020). "Knockout of CBS and CSE in animal models leads to liver steatosis, further strengthening the potential link between the TSP and NAFLD." (PMID 33807699, 2021).
Hyperglycemia (7 papers, 2010 to 2025). An increased concentration of glucose in the blood. "Thus, the hyperglycemia caused by sub-chronic administration in the high-dose KRG groups may be associated with increased H2S synthesis via CBS and CSE in the liver, given that CSE is an important H2S-producing enzyme that can be upregulated by NO26." (PMID 34117292, 2021). "The two-fold increase in glucose and Hcy level in Ins2+/-/CBS+/- suggests synergism in HHcy and hyperglycemia." (PMID 20828387, 2010). "To investigate individual and synergistic effect of hyperglycemia and HHcy, we cross-bred Akita with CBS+/- to obtain four types of offspring: Ins2+/+/CBS+/+ (WT); Ins2+/-, CBS+/+ (Akita); Ins2+/+/CBS+/- (CBS mutant) and Ins2+/-/CBS+/- (double knock out)." (PMID 20828387, 2010). "The four groups obtained by cross- breeding Ins2+/- with CBS+/- provides insight into the independent and synergistic implications of HHcy and hyperglycemia on diabetic cardiomyopathy." (PMID 20828387, 2010). "The induction of MMP-9 in HHcy (CBS+/-) and hyperglycemia (Ins2+/-) due to oxidative stress is in line with the earlier findings." (PMID 20828387, 2010). "Conversely, we further confirmed a strong correlation between CBS expression and hyperglycaemia." (PMID 35453313, 2022). "After exploring the role of each protein and its association with hyperglycemia after KRG administration for 4 weeks, we focused on the most upregulated protein, CBS, and validated the accuracy of the TMT-labeled quantitative proteomics results using Western Blot." (PMID 34117292, 2021). "Interestingly, the total urinary protein was almost two fold increased in Ins2+/-/CBS+/- suggesting synergistic effect of hyperglycemia and HHcy." (PMID 20828387, 2010). "Therefore, the increase in CBS and CSE protein expression can be a compensatory response resulting from oxidative stress induced by hyperglycemia, and oxidative stress-reduced H2S production." (PMID 25727037, 2015).
preeclampsia (7 papers, 2019 to 2026). Preeclampsia is a hypertensive disorder of pregnancy that is characterized by new-onset hypertension with proteinuria presenting after 20 weeks of gestation, and depending on mild or severe forms may initially present with severe headache, visual disturbances, and hyperreflexia. "In addition, women diagnosed with preeclampsia present a decrease in plasma H2S levels, linking this decrease to a diminution in CBS and CSE enzymatic activities." (PMID 38276547, 2024). "As lactation failure can be managed in clinical settings, this study may help the understanding of the pathophysiology of preeclampsia in relationship to homocysteine and transsulfuration pathway mediated by CBS and CTH." (PMID 31319489, 2019). "Within the placenta, CBS and CSE proteins were localized to fetal endothelial cells, and decreases in placental mRNA expression of CBS and CSE have been documented in preeclampsia." (PMID 34831277, 2021). "The uterine artery CBS expression increases during pregnancy, whereas decreased maternal serum sulfide and reduced placental CBS and CSE correlate with preeclampsia." (PMID 32630731, 2020). "This unexpected result would indicate that simply measuring placental CSE or CBS activities or even their protein levels to determine the involvement of placental H2S production in physiological or pathological pregnancies, such as preeclampsia, would not be sufficient." (PMID 38276547, 2024).
type 2 diabetes (7 papers, 2010 to 2023). "In this study, we observed that levels of CSE, and CBS to a lesser extent, were reduced in synovial tissue from OA patients with type II diabetes." (PMID 37335394, 2023). "To date, scarce information is available about the HHcy effect on insulin secretion, and the link between CBS activity and the setting of type 2 diabetes is still unknown." (PMID 35681432, 2022). "In Zucker diabetic fatty rats representing a type 2 diabetes model and in a type 1 diabetes animal model with streptozotocin an impaired insulin secretion and signaling and an increased hepatic gene expression of CBS and BHMT representing the branch-point enzymes of C1-metabolism have been reported." (PMID 23472083, 2013). "CBS is mainly expressed in the liver, which is the key organ maintaining methionine/Hcy homeostasis; HHcy has frequently been associated with non-alcoholic fatty liver disease (NAFLD) and type 2 diabetes (T2DM)." (PMID 35681432, 2022). "We have previously reported that CBS and CSE expression, and generation of H2S, are reduced in the renal cortexes of aged mice, marmosets, and mice with type 1 and type 2 diabetes." (PMID 33400689, 2021). "The specific molecular mechanisms of by which SCU improve type 2 diabetes model were to upregulate the key enzyme of Hcy metabolism MTHFR, MTR, CBS and CSE with their cofactor VitB12, VitB6 and folic acid." (PMID 33362535, 2020). "Among NW subjects, we observed nominal association of MTHFR-rs1801133, MTHFR-rs9651118, CHDH-rs4563403, CBS-rs706208, and MTHFD1L-rs1555179 with type 2 diabetes (P value range= 0.002–0.04)." (PMID 21960995, 2012).
chronic myeloid leukemia (6 papers, 2021 to 2024). "In Chronic Myeloid Leukemia, high CBS levels are associated with increased cell proliferation, suggesting CBS as a potential therapeutic target." (PMID 39062461, 2024). "CBS expression is also elevated in chronic myeloid leukaemia, and knockdown of CBS or AOAA treatment promotes apoptosis and triggers S‐phase arrest by regulating cleaved caspase‐9, Bax, cyt C, and NF‐κB." (PMID 36929586, 2023). "Our study suggests that inhibition of CBS induces cell apoptosis, as well as limits cell proliferation and migration, a potential target for the treatment of chronic myeloid leukemia." (PMID 33558454, 2021). "In addition, CBS contribution into the development of tumors and proliferation of malignant cells has been described for chronic myeloid leukemia and breast, ovarian, and colon cancer." (PMID 36361596, 2022). "Inhibition of CBS induced apoptosis and reduced cell proliferation in chronic myeloid leukemia." (PMID 35204649, 2022). "It has been revealed that inhibition of CBS by AOAA decreases the endogenous H2S levels, promotes mitochondria-mediated apoptosis, and inhibits the transcriptional activity of nuclear factor-kappa B in chronic myeloid leukemia-derived K562 cells." (PMID 35795862, 2022). "However, the role of CBS and H2S in chronic myeloid leukemia (CML) remains elusive." (PMID 33558454, 2021).
endothelial dysfunction (6 papers, 2012 to 2025). In vascular diseases, endothelial dysfunction is a systemic pathological state of the endothelium (the inner lining of blood vessels) and can be broadly defined as an imbalance between vasodilating and vasoconstricting substances produced by (or acting on) the endothelium. "Mutations in the CBS gene are known to cause endothelial dysfunction responsible for cardiovascular and neurovascular diseases, and CBS/H2S pathway interacts with mitochondrial function and ER-mitochondrial tethering, therefore interfering with endothelial cell dysfunction-related pathologies." (PMID 36034427, 2022). "On the other hand, CBS knockdown increased the vulnerability of human endothelial cells to homocysteine, a well-known inducer of cellular senescence, which was described by others as risk factor predisposing to endothelial dysfunction and disease." (PMID 23117410, 2012). "In HHcy, reduced expression of CBS and CSE results in decreased H2S production, impairing endothelial repair mechanisms and worsening endothelial dysfunction." (PMID 39898976, 2025). "CBS expression decreased gradually with cellular aging in human umbilical vein endothelial cells (HUVEC), which are used as a model for vascular aging and endothelial dysfunction." (PMID 23117410, 2012).
Ectopia lentis (5 papers, 2015 to 2024). "Ectopia lentis may be the first and only sign of CBS deficiency." (PMID 27778219, 2017).
Insulin resistance (5 papers, 2010 to 2023). Increased resistance towards insulin, that is, diminished effectiveness of insulin in reducing blood glucose levels. "It has been suggested that insulin modulates CBS activity, and modulation becomes disturbed in insulin resistance." (PMID 37424916, 2023). "Our results identified the CBS gene as being one of several genes related to insulin resistance and basal insulinemia." (PMID 35681432, 2022). "Through the use of three mouse strains on HFD, transcriptomic analysis identified that the CBS gene expression in the islet correlated positively with insulin resistance and basal insulinemia." (PMID 35681432, 2022). "Overexpression of CBS in PVN reduces obesity and insulin resistance induced by a high-fat diet (HFD)." (PMID 34335475, 2021). "HHcy has been demonstrated to promote insulin resistance in both humans and rodents, however, the consequences of an inborn defect in an enzyme in sulfur amino acid metabolism, CBS, on glucose homeostasis in mice have not been described." (PMID 35681432, 2022). "Mechanistically, leptin up-regulates CBS expression through FOXO3a, promotes pre-TRH production by inhibiting the mTOR pathway, and then increases TH production and decreases corticosterone production, thus reducing fat deposition and improving insulin resistance induced by FHD." (PMID 34335475, 2021).